ARL8B (ARF like GTPase 8B)
Description:
Small GTPase which cycles between active GTP-bound and inactive GDP-bound states. In its active state, binds to a variety of effector proteins playing a key role in the regulation of lysosomal positioning which is important for nutrient sensing, natural killer cell-mediated cytotoxicity and antigen presentation. Along with its effectors, orchestrates lysosomal transport and fusion. Localizes specifically to lysosomal membranes and mediates anterograde lysosomal motility by recruiting PLEKHM2, which in turn recruits the motor protein kinesin-1 on lysosomes. Required for lysosomal and cytolytic granule exocytosis. Critical factor involved in NK cell-mediated cytotoxicity. Drives the polarization of cytolytic granules and microtubule-organizing centers (MTOCs) toward the immune synapse between effector NK lymphocytes and target cells. In neurons, mediates the anterograde axonal long-range transport of presynaptic lysosome-related vesicles required for presynaptic biogenesis and synaptic function (By similarity). Also acts as a regulator of endosome to lysosome trafficking pathways of special significance for host defense. Recruits RUFY1 onto early endosomes regulating endosomes to trans-Golgi network proteins retrieval. Regulates cargo trafficking to lysosomes by binding to PLEKHM1 and recruiting the HOPS subunit VPS41, resulting in functional assembly of the HOPS complex on lysosomal membranes. Plays an important role in cargo delivery to lysosomes for antigen presentation and microbial killing. Directs the intersection of CD1d with lipid antigens in lysosomes, and plays a role in intersecting phagosomes with lysosomes to generate phagolysosomes that kill microbes. Involved in the process of MHC II presentation. Regulates the delivery of antigens to lysosomes and the formation of MHC II-peptide complexes through the recruitment of the HOPS complex to lysosomes allowing the fusion of late endosomes to lysosomes (By similarity). May play a role in chromosome segregation. (Microbial infection) During Mycobacterium tuberculosis (Mtb) infection, is required for plasma membrane repair by controlling the exocytosis of lysosomes in macrophages. ARL8B secretion pathway is crucial to control the type of cell death of the M.tuberculosis-infected macrophages, distinguishing avirulent from virulent Mtb induced necrotic cell death. (Microbial infection) During infection, coronaviruses such as SARS-CoV-2 and the chaperone HSPA5/GRP78 are probably co-released through ARL8B-dependent lysosomal exocytic pathway for unconventional egress.
Synonyms: ARL10C; GIE1; FLJ10702
Tractability: Small molecule: a structure with a bound ligand is known. PROTAC: UniProt records ubiquitination sites on it; ubiquitination databases record sites on it; its protein half-life has been measured.
Gene: Protein-coding gene on chromosome 3 (5,122,249 to 5,180,911, forward strand). Ensembl gene ENSG00000134108.
Subcellular location: Late endosome membrane; Lysosome membrane; Cytoplasm, cytoskeleton, spindle; Cell projection, axon; Synapse; Cytolytic granule membrane; Early endosome membrane
Gene Ontology:
Molecular function: alpha-tubulin binding; beta-tubulin binding; G protein activity; GDP binding; GTP binding; GTPase activity; protein binding
Biological process: antigen processing and presentation following phagocytosis; autophagosome-lysosome fusion; calcium ion regulated lysosome exocytosis; chromosome segregation; early endosome to Golgi transport; endosome to lysosome transport of low-density lipoprotein particle; late endosome to lysosome transport; lysosome localization; natural killer cell mediated cytotoxicity; phagosome-lysosome fusion; plasma membrane repair; protein localization to early endosome; viral exocytosis; anterograde axonal transport; antigen processing and presentation of polysaccharide antigen via MHC class II; protein transport
Cellular component: cytolytic granule membrane; cytoplasm; early endosome membrane; extracellular exosome; late endosome membrane; lysosomal membrane; lysosome; membrane; midbody; spindle midzone; synapse; axon; axon cytoplasm; cytosol; spindle
Genetic constraint (gnomAD): Loss-of-function variants: 5 observed, 15.07 expected, observed/expected ratio (o/e) 0.33, 90% interval 0.17 to 0.7. The upper end of that interval is the gene's LOEUF score, 0.7, which puts it in group 2 of 6, group 1 being the genes least tolerant of losing a copy. Missense variants: 69 observed, 109.11 expected, observed/expected ratio (o/e) 0.63, 90% interval 0.52 to 0.77. Synonymous variants: 41 observed, 39.57 expected, observed/expected ratio (o/e) 1.04, 90% interval 0.81 to 1.34.
Homologues: Orthologues: chimpanzee ARL8B (100% identical), dog ARL8B (100% identical), macaque ARL8B (100% identical), mouse Arl8b (100% identical), rat Arl8b (100% identical), guinea pig ARL8B (99% identical), zebrafish arl8ba (97% identical), tropical clawed frog arl8b (96% identical), zebrafish arl8bb (94% identical), pig ARL8B (67% identical). Paralogues in human: ARL8A (92% identical), ARL3 (35% identical), ARF1 (32% identical), ARF3 (32% identical), ARL2 (32% identical), ARL6 (32% identical), ARF6 (31% identical), ARFRP1 (31% identical), ARL4C (31% identical), TRIM23 (31% identical), ARL1 (30% identical), ARL4A (30% identical), and 18 more.